TGFB2 (transforming growth factor beta 2)
Diseases named in the same sentence as TGFB2 in open-access papers (continued):
Sharing a sentence is not in itself a finding about the gene and the disease.
lung carcinoma (28 papers, 2012 to 2025). "Next, we evaluated the diagnostic values of the CCNA2 and TGFB2 risk genes through ROC curve analysis of the lung cancer diagnoses." (PMID 33195410, 2020). "Our in vitro experiments demonstrated that COX6A1 knockdown in lung cancer cells led to the upregulation of TGFB2, CXCL12, and FGF2." (PMID 40331946, 2025). "However, we found reduced TGFβ2 expression to be correlated with poorer patient prognosis in lung cancer (OS HR = 0.83, 95% CI = 0.73–0.94, P = .0029; PFS HR = 0.78, 95% CI = 0.64–0.94, P = .01)." (PMID 32530106, 2020). "However, this actually fitted our conclusion more favorably: GATA4 is inactive and at the same time WNT7B and TGFB2 is hyperactive in lung cancer cells." (PMID 30971692, 2019). "Moreover, a vaccine targeting TGFβ2 (belagenpumatucel-L) has undergone phase III clinical trials in lung cancer patients, where it has yielded promising results." (PMID 27586372, 2017). "GATA4 is an important tumor suppressor in lung cancer and could induce the senescence of lung cancer cells via upregulating several miRNAs that target TGFB2 mRNA and ensuing downregulation of WNT7b expression, suggesting WNT7b may play a carcinogenic role in lung cancer." (PMID 37486552, 2023). "Next, to identify the specific source of TGF-β at the cellular level, we analyzed the expression of TGFB1, TGFB2, and TGFB3 using the sc-RNAseq datasets of 33K PBMC and 52K lung cancer cells." (PMID 35069521, 2021). "Conversely, knockdown of GATA4 expression level upregulated TGFB2 and WNT7B transcription in lung cancer cell line H226, supporting that GATA4-TGF-β2-Wnt-7b signaling axis is common to lung cancer cells." (PMID 30971692, 2019). "Our model predicts that GATA4 expression level is inversely correlated with those of TGFB2 and WNT7B in lung cancer." (PMID 30971692, 2019). "By downregulating TGFB2 level via miRNAs, GATA4 decreases expression of WNT7B to induce senescence in lung cancer cells." (PMID 30971692, 2019). "Our above data have shown that GATA4 expression downregulated TGFB2 and the ensuing downstream WNT7B signaling in A549 lung cancer cell line." (PMID 30971692, 2019). "In addition, knockdown of FLJ20420 expression also significantly increased the expression of PRKCBP2, TGFBR1, TGFB2, CLCN4, TRAF3, MYLK and ACTA2, while decreasing the expression of SMAD5 and prot-LBC, resulting in an increased apoptotic potential in FLJ20420-silenced lung cancer cells." (PMID 22567091, 2012). "We also found significant negative correlation of expression level between GATA4 and TGFB2 and between GATA4 and WNT7B among non-manipulated lung cancer cell lines and normal lung epithelial cell lines." (PMID 30971692, 2019).
ovarian carcinoma (26 papers, 2013 to 2025). A malignant neoplasm originating from the surface ovarian epithelium. "It proposes an additional set of four TGFB2-independent prognostic markers to guide treatment for patients with Taxol-treated ovarian cancer." (PMID 41465326, 2025). "We have extended these studies to utilize a bioinformatic-driven approach to characterize the impact of TGFB2 mRNA, in combination with potential prognostic markers, on OS in ovarian cancer patients from The Cancer Genome Atlas (TCGA) database." (PMID 41465326, 2025). "In ovarian cancer, TGFB2 is overexpressed and plays a key role in ovarian oncogenesis by regulation of an epithelial-to-mesenchymal transition." (PMID 34136553, 2021). "Although the role of TGFβ in ovarian cancer has been studied extensively, the function of TGFβ1 and TGFβ2 in exosomes remains to be explored to understand how these cytokines contribute to EMT in ovarian cancer." (PMID 29221185, 2017). "Ovarian cancer patients with high TGFB2 and MAL2 mRNA levels showed the longest OS improvement." (PMID 41465326, 2025). "Similarly, the Kaplan‐Meier plotter database found elevated TGFβ2 to correlate with poor GC and ovarian cancer outcome." (PMID 32530106, 2020). "However, TGFβ2 induced ovarian cancer cells into an incomplete or only partial EMT status." (PMID 29221185, 2017). "Previous studies showed that TGFβ1 and TGFβ2 were both capable of inducing complete EMT in OVCA429, a clear-cell ovarian cancer cell line, but a partial EMT was observed in OVCAR3, a serous ovarian cell." (PMID 29221185, 2017). "A multivariate analysis revealed that, after controlling for TGFB2 expression, four genes (CLIC3, ANPEP/LAP1, RIN2, and EMP1) showed negative correlations between mRNA expression and OS across all expression levels in an ovarian cancer cohort." (PMID 41465326, 2025). "To expand the list of potential biomarkers for ovarian cancer patients, we sought to identify biomarkers independent of TGFB2 mRNA expression using a Cox proportional hazards model." (PMID 41465326, 2025). "Similarly, in our study, TGFβ2 promoted the SKOV-3 and CAOV-3 cells to an uncomplete EMT phenotype, which may also be because we chose two serous cancer cell lines, the most common histologic subtype in ovarian cancer." (PMID 29221185, 2017). "TGFB1 and TGFBR1 expression did not affect survival (data not shown), while TGFB2, TGFB3, TGFBR2, and TGBR3 overexpression decreased patient survival among ovarian cancer patients when the microarray data was assessed." (PMID 38196068, 2024).
hepatocellular carcinoma (25 papers, 2016 to 2025). A malignant tumor that arises from hepatocytes. "Strategies such as TGF‐β signalling blockade, knockdown of hepatoma‐intrinsic Mettl1 or Tgfb2, or interruption of the METTL1‐TGF‐β2‐PMN‐MDSC axis can mitigate tumour progression induced by iRFA and restore the CD8+ T cell population." (PMID 38943267, 2024). "SHP-1 inhibits HOXA10 and TGFβ2 which in turn regulates the expression of the migration-associated proteins, MMP2/9, and the migration of hepatocellular carcinoma cells." (PMID 38644382, 2024). "'Circ-SPECC1 Modulates TGFβ2 and autophagy under oxidative stress by sponging miR-33a to promote hepatocellular carcinoma tumorigenesis' by Bin Zhang, Zhiyi Liu, Kuan Cao, Wengang Shan, Jin Liu, Quan Wen, Renhao Wang, Cancer Med 2020, 9: 5999-6008." (PMID 38108531, 2023). "Prior work showed that RALYL stabilizes Tgfb2 transcripts in hepatocellular carcinoma, thus increasing the stemness of HCC cells." (PMID 37591832, 2023).
bladder cancer (24 papers, 2015 to 2025). "TGFβ2 has shown mixed expression changes after PEMF treatment in cells, but its promotion is well implicated in higher bladder cancer stages, grades, and invasion potential." (PMID 40278322, 2025). "Supporting this observation, TGFB2–Smad3 pathway has been demonstrated to promote proliferation and epithelial–mesenchymal transition in several cancers, recently also in bladder cancer." (PMID 35841413, 2022). "To further investigate whether hub genes have an impact on the prognosis of bladder cancer, we performed survival analysis of CXCL8, MDM2, TGFB2, FN1, TIMP1, and RPL22L1, and their impact on tumor stage using TCGA database." (PMID 34276798, 2021).
colorectal cancer (22 papers, 2018 to 2024). A primary or metastatic malignant neoplasm that affects the colon or rectum. "In colorectal cancer, cancer-associated fibroblasts (CAFs)-secreted TGFB2 and hypoxia-inducible factor (HIF-1α) interact to activate the expression of hedgehog transcription factor GLI2 in cancer stem cells, resulting in intrinsic resistance to chemotherapy." (PMID 38914663, 2024). "TGFB2, one of the major members of TGF-β signaling, is critically associated with the progression and susceptibility of colorectal cancer." (PMID 35991839, 2022). "Within the TGFb super family, TGFb1, TGFb2, and TGFb3 play roles in these oncogenic processes and elevated systemic TGFb levels have been found to be correlate to poor prognosis factor in colorectal cancer." (PMID 30728909, 2019). "While DNA methylation in genes MDF1, SSTR2, CMTM3, TGFB2, and NDRG4 is a potential marker for the detection of colorectal cancer in the early stages of its development, hypermetylation in gene CLDN11 is associated with metastasis and poor prospect of patient survival with colorectal cancer." (PMID 32370233, 2020).
myopia (22 papers, 2009 to 2025). "Interestingly, the SNPs pinpointing chromosome 1q41 in our study are 1 Mb away from the transforming growth factor beta 2 gene (TGFβ2) which has been implicated in the down-regulation of mRNA levels in myopia progression of an induced tree shrew myopia model." (PMID 22685421, 2012). "These included FBN1, ADAMTS2 and TGFB2 which associate with connective tissue disorders (Marfan, Ehlers-Danlos and Loeys-Dietz syndromes), and the LUM-DCN-KERA gene complex involved in myopia, corneal dystrophies and cornea plana." (PMID 29760442, 2018). "This network was composed primarily of genes involved in immune-mediated ECM remodeling, and included connections with many intermediate genes that have been strongly linked to myopia in previous targeted studies (e.g. MMP2, TGFB1, TGFB2, FGF2, INS, and IGF2)." (PMID 28852117, 2017). "Here we presented the changes in mRNA expression levels of three genes (MMP2, TIMP2, and TGFB2), all known to participate in extracellular matrix organization, at five regions of the cornea and sclera in chickens developing high myopia and astigmatism induced by form deprivation." (PMID 28900109, 2017). "The intragenic TGFB2 deletion was also present in his clinically affected father (clinical features include aortic root aneurysm requiring surgery at age 31 and aortic dissection at age 46) and his 11‐year‐old sister (features consisted of pectus deformity and highly arched palate and mild myopia)." (PMID 29907982, 2018).
diabetes (20 papers, 2010 to 2025). "A detailed ceRNA network was constructed, consisting of nine lncRNAs, nine mRNAs, and five miRNAs with Rno-miR-10b-5p and Tgfb2 identified as key regulators of endothelial progenitor cell dysfunction in diabetes." (PMID 39498440, 2024). "TGFB2 encodes a secreted ligand of the transforming growth factor-beta (TGF-β) superfamily of proteins, which is involved in the pathogenesis of diabetes and complications." (PMID 36544488, 2022). "Cone communicates with microglia through secreted TGFβ2 instead of TGFβ1, suggesting a novel target sites of TGFβ mediating the effects of microglia under diabetes mellitus." (PMID 34434927, 2021). "Each of these genes has been proposed to be involved in angiogenesis or regulation of blood vessels; IGFBP3 and TGFB2 have also been proposed as genes related to diabetes." (PMID 21179236, 2010). "The results suggest that LOX, HIF1α, THBS1, TGFβ2, and ITGβ1 may be involved in the diabetes‐induced downregulation of FGF9, thus promoting the development of renal EMT." (PMID 40977522, 2025). "Taken together, our data imply that AGEs in the lens capsule promote the TGFβ2‐mediated fibrosis of lens epithelial cells during PCO and suggest that AGEs in BMs could have a broader role in aging and diabetes‐associated fibrosis." (PMID 26853893, 2016). "When we analyzed TGFβ-associated genes, we were astonished that several triggers like TGFβ2 and TGFBI were significantly activated by diabetes, while several suppressors like TGIF1 and TGIF2 were significantly deactivated by diabetes." (PMID 35935990, 2022). "In kidneys, AcSDKP also restored the diabetes-suppressed FGFR1 and P-MAP4K4 levels and the diabetes-induced TGFβ1 and TGFβ2 expression." (PMID 28771231, 2017). "In the hearts, AcSDKP reversed the diabetes-suppressed FGFR1 and P-MAP4K4 levels and the diabetes-induced TGFβ2 levels." (PMID 28771231, 2017). "Based on our finding in this study that AGEs promote the TGFβ2‐mediated EMT response in HLE cells, it can be speculated that the PCO rate could be higher in individuals with diabetes than in individuals without diabetes." (PMID 26853893, 2016).
gastric cancer (20 papers, 2019 to 2025). A primary or metastatic malignant neoplasm involving the stomach. "TGFβ2 was closely related to the gastric cancer microenvironment, and functional enrichment analysis of TGFβ2 and TGFβ2-associated methylation was performed to explore the possible mechanisms of TGFβ2 action in gastric cancer." (PMID 35620459, 2022). "In the gastric cancer microenvironment TGFβ2 was associated with high levels of multiple immune cell infiltration and cytokine expression, and high TGFβ2 expression was significantly and positively correlated with stemness markers, stromalscore and EMT." (PMID 35620459, 2022). "Also high expression of TGFβ2 in the gastric cancer microenvironment was associated with higher levels of stromalscore and CAFs infiltration, and similar results were seen in the pan-cancer and multiple gastric cancer datasets." (PMID 35620459, 2022). "As we found TGFβ2 expression to be linked with poor gastric cancer patient prognosis, we next explored the underlying mechanisms via using the Kaplan‐Meier plotter database to assess the relationship between TGFβ2 expression and patient clinicopathological findings." (PMID 32530106, 2020). "In gastric cancer, TGFβ2 correlated with poorer prognosis than TGFβ1, and in malignant gliomas and nasopharyngeal carcinoma, TGFβ2 was associated with malignancy." (PMID 39992949, 2025). "We analyzed the Harbin Medical University Cancer Hospital (HMUCH) sequencing data and used public data to explore the potential function and prognostic value of TGFβ2 and its methylation in gastric cancer." (PMID 35620459, 2022). "The expression levels of TGFβ2 in gastric cancer tissues were significantly higher in the datasets GSE184336, GSE29272 and STAD than in normal tissues adjacent to the cancer." (PMID 35620459, 2022). "In view of the important role of TGFβ in EMT, we used small interfering RNA (siRNA) to reduce TGFβ1, TGFβ2 and TGFβ3 gene expression in gastric cancer cells." (PMID 36119489, 2022). "In view of the relationship between TGFβ2 expression and TGFβ2 methylation, the results all emphasized that high TGFβ2 expression is a poor prognostic factor for gastric cancer, which is consistent with the results of previous research reports." (PMID 35620459, 2022). "We verified the protein expression level of TGFβ2 in gastric cancer tissues, and the results of IHC experiments showed that TGFβ2 was mainly distributed in cancer cells, with a small amount of distribution in the mesenchyme." (PMID 35620459, 2022). "In conclusion, high expression of TGFβ2 and hypomethylation of TGFβ2 are factors of poor prognosis in gastric cancer." (PMID 35620459, 2022). "Transwell assay examined the change of gastric cancer cell migration ability in TGFβ experimental group and control group (HSA), and the migration ability of gastric cancer cells was enhanced under TGFβ1, TGFβ2 and TGFβ3 active protein stimulation conditions." (PMID 36119489, 2022). "The results showed that TGFβ2 was highly expressed in gastric cancer and was a poor prognostic factor." (PMID 35620459, 2022). "The results of Western blot assay showed that the protein expression level of TGFβ2 was higher in gastric cancer tissues than normal tissues, which was consistent with the results of transcriptome sequencing level (GSE184336)." (PMID 35620459, 2022). "TGFβ1, TGFβ2 and TGFβ3 were significantly positively correlated with immune cell infiltration in multiple gastric cancer datasets." (PMID 36119489, 2022). "Survival analysis showed that patients with high levels of TGFβ2 gastric cancer had shorter survival times and those with high TGFβ2 methylation scores had longer survival times." (PMID 35620459, 2022). "The results showed that in gastric cancer TGFβ1, TGFβ2 and TGFβ3 expressions were strongly correlated with most of the immune cell infiltration levels." (PMID 36119489, 2022).
gastric cancer (continued). "Given the strong correlation between TGFβ2 and immune cell infiltration and its important role in the regulation of immune cell function in gastric cancer, TGFβ2 is an important factor that cannot be ignored in gastric cancer immunotherapy." (PMID 35620459, 2022). "Firstly, immunohistochemical experiments were performed on paraffin sections of gastric cancer to observe the main distribution of TGFβ1, TGFβ2 and TGFβ3 proteins in gastric cancer tissues." (PMID 36119489, 2022). "To verify the promoting effect of TGFβ on EMT, we added TGFβ1, TGFβ2 and TGFβ3 active proteins to the culture medium, respectively, and cultured gastric cancer cells in TGFβ environment to detect the changes of cancer cell phenotype." (PMID 36119489, 2022). "Survival analysis of GSE184336 showed shorter survival times in patients with high TGFβ1 and TGFβ2 expression, and similar results were seen in several gastric cancer datasets set." (PMID 36119489, 2022). "The high expression of TGFβ2 in gastric cancer tissue affects the tumor microenvironment and the level of immune cell infiltration by regulating DNA damage, angiogenesis, inflammation and EMT." (PMID 35620459, 2022). "TGFβ2 was an independent prognostic factor for patients with gastric cancer in both the STAD and GSE62254 datasets in a multifactorial survival analysis." (PMID 35620459, 2022). "In contrast, the migration ability of gastric cancer cells was reduced and statistically significant after silencing of TGFβ1, TGFβ2 and TGFβ3 genes." (PMID 36119489, 2022). "TGFB2 and VEGFB were selected as risk predictors for both overall and disease-free survival highlighting the role of TGFB and PI3K/AKT pathway in gastric cancer." (PMID 34332586, 2021). "Simultaneously, TGFB2, VEGFB, COL10A1, ERG1 and EFNA5 composed risk model is a promising tool for assessment of gastric cancer survival." (PMID 34332586, 2021). "This suggests that TGFβ2 plays a strong role in regulating immune cell infiltration in gastric cancer, with a particularly strong effect on macrophage infiltration." (PMID 32530106, 2020). "Our results offer novel insights into the functional role of TGFβ2 in gastric cancer, thereby highlighting a potential mechanistic basis whereby TGFβ2 influences immune cell interaction with tumours." (PMID 32530106, 2020). "We further found TGFβ2 expression to correlate with each N stage, which corresponds to the degree of lymph node metastasis in gastric cancer patients." (PMID 32530106, 2020). "For instance, HOXA10 promotes gastric cancer EMT via the TGFB2/Smad/METTL3 signaling axis." (PMID 38178023, 2024). "In this study, we comprehensively analyzed the relationship between TGFβ2 and TGFβ2 methylation levels and the microenvironmental characteristics of gastric cancer based on sequencing data from the Harbin Medical University Cancer Hospital (HMUCH) and public databases." (PMID 35620459, 2022). "In addition, high levels of TGFβ2 were a factor of poor prognosis in patients with gastric cancer, which is consistent with the results reported in previous studies." (PMID 36119489, 2022). "The expression levels of TGFβ2 were also validated in gastric cancer tissues." (PMID 35620459, 2022). "However, the potential functions and mechanisms of TGFβ1, TGFβ2 and TGFβ3 in gastric cancer progression and tumor immunology are unclear." (PMID 36119489, 2022). "TGFβ2 was negatively correlated with mRNAsi and significantly positively correlated with stemness markers (DCLK1 and CD44) in this study, so TGFβ2 may be important factor in maintaining tumor stemness and promoting tumor differentiation in gastric cancer." (PMID 35620459, 2022). "However, the potential functions and mechanisms of TGFβ2 and TGFβ2 methylation involved in gastric cancer progression are unclear." (PMID 35620459, 2022).